HMGB1 (high mobility group box 1)
Diseases named in the same sentence as HMGB1 in open-access papers (continued):
Sharing a sentence is not in itself a finding about the gene and the disease.
tumor (continued). "Moreover, the ethanol-treated tumor cells expressed “eat-me” signals such as calreticulin (CRT) on the cell surface and released immunostimulatory factors such as heat shock protein (HSP)90α and high-mobility group box 1 (HMGB1)." (PMID 23717436, 2013). "Currently, the redox state of HMGB1 released from IR exposed tumor cells has not been determined." (PMID 22891162, 2012). "However, several studies have demonstrated that HMGB1 mediates endogenous Toll-like receptor (TLR) activation, and its increased interaction might enhance the tumor regression by immunoadjuvant effects after conventional chemo- or radiotherapy." (PMID 19476625, 2009). "However, there is no method to distinguish whether the released HMGB1 is from tumor-derived or normal cell-derived HMGB1, and the exact amount of HMGB1 released cannot be measured in-vivo studies." (PMID 40583575, 2025). "However, the distinct functional differences between extracellular and intracellular HMGB1 suggest that targeting HMGB1 may not consistently achieve the desired therapeutic effects across different stages of tumor development." (PMID 39893499, 2025). "High mobility group box 1 (HMGB1) is a nonhistone DNA-binding protein that is widely expressed in the nucleus, cytoplasm, and extracellular region and has diverse functions, such as influencing cell migration, cell differentiation, inflammation, and tumor progression." (PMID 41164196, 2025). "Whether cells are necrotic or necroptotic, they release HMGB1 as a DAMP in the extracellular milieu, triggering complex signaling through receptors like RAGE and TLR4 that can either activate immune response or paradoxically enhance tumor survival and foster therapy resistance." (PMID 41465435, 2025). "Ablated tumor cells could transition from a non-immunogenic state to an immunogenic one, characterized by the release of secretory damage-associated molecular patterns (DAMPs), including HSP70, HSP90, CRT, and HMGB1." (PMID 38994019, 2024). "Another interesting finding in our results is that the four prognostic PRGs (BAK1, CYCS, HMGB1, and NLRP1) were significantly correlated with immune cell infiltration, which further confirmed that pyroptosis in immune cells might participate in regulating the tumour microenvironment." (PMID 37337018, 2023). "However, with there being scarce evidence regarding the impact of ferroptosis-released HMGB1 on tumor growth in vivo, it is not enough to conclude that HMGB1 plays a beneficial role in the ferroptosis-induced immune response for antitumor therapy, and further investigations are still required." (PMID 37325669, 2023). "We evaluated in murine tumor cell lines B16F10, 4T1, and CT26 whether electrochemotherapy triggered changes in immunogenic cell death DAMPs: calreticulin, ATP, high mobility group box 1 (HMGB1), and four immunologically important cellular markers: MHCI, MHC II, PD-L1 and CD40." (PMID 38292489, 2023). "Therefore, targeting RAGE, HMGB1, and S100A8/A9 will not only reduce immune suppression and facilitate antitumor immunity but may also delay tumor progression by neutralizing the many other mechanisms by which these molecules promote tumor growth." (PMID 36831371, 2023). "However, HMGB1 might promote tumor development rather than activating immune responses against premalignant cells as chemically-induced skin and inflammation-induced liver cancer development was inhibited in mice deficient for the HMGB1 receptor RAGE." (PMID 36032129, 2022). "Interestingly, the high expression of HMGB1 is related to the significantly increased survival rate for THYM, based on the OS result for HMGB1, which may indicate the potential function of HMGB1 in specific tumours." (PMID 35765707, 2022). "Hence, the capacity of Rb4 to lyse tumor cells in a non-physiological (unconventional) fashion may contribute to its pro-immune effects through the liberation of DAMPs such as HMGB1 and calreticulin." (PMID 35190586, 2022).
tumor (continued). "In view of the extracellular expression of HMGB1 and overexpression of TIM3 on the immune cell membrane, it may be postulated that the HMGB1-TIM3 complex has a role in generating an immune deficit in the tumor surveillance mechanism, allowing tumoral cells to escape the antitumoral response." (PMID 35207500, 2022). "However, the DNA methylation level of HMGB1 for these three tumours are not consistent." (PMID 35765707, 2022). "Further rescue experiments showed that, compared with the control group, HMGB1 could reduce the inhibitory effect of overexpression of miR-495-3p on the proliferation and migration of CRC cells, and this consequence was also verified in vivo by our tumour formation experiment in nude mice." (PMID 35354479, 2022). "Patients with tumor antigen-specific T‐cell response showed significantly higher levels of HMGB1 at the end of treatment compared to patients without this specific T‐cell response, probably indicating better anti-tumor immune responses possibly related to better tumor control." (PMID 34671818, 2022). "Notably, HMGB1 released from dying tumor cells rather than intracellular HMGB1 could promote neosis‐based tumor repopulation, and the latter could be suppressed by the use of HMGB1 inhibitors." (PMID 33523579, 2021). "Extracellular HMGB1 can also bind to TLR2 (Toll-like receptor-2), TLR4, and RAGEs, and the impediment of RAGE–HMGB1 interaction could block the activation of p44/p42, p38, and Stress-activated protein kinases (SAPK)/JNK MAP kinases, which were significantly conducive to tumor proliferation." (PMID 33466626, 2021). "Moreover, Tim-3 can interact with high-mobility group protein B1 (HMGB1) to interfere with the recruitment of nucleic acids into DC endosomes and attenuate the therapeutic efficacy of DNA vaccination and chemotherapy by diminishing the immunogenicity of nucleic acids released from dying tumor cells." (PMID 33868234, 2021). "Tim-3 is highly expressed on tumor-infiltrating DCs and may act as a molecular sink of the alarmin HMGB1, with the recruitment of nucleic acids released from dying tumor cells, but the binding site of the Tim-3/HMGB1 interaction has not been identified." (PMID 33868234, 2021). "However, RAGE expression was only found on ductual cells and Kupffer’s cells but not on hepatoctyes, suggesting that HMGB1 might promote hepatic tumor growth through a paracrine mode, which altered the tumor microenvironment." (PMID 32382012, 2020). "We hypothesize that the ability of xCT immunotargeting to inhibit the HMGB1/TLR2 axis may contribute to its therapeutic activity and suggest that it would be worth developing combined therapies targeting these two mechanisms responsible for tumor survival and progression." (PMID 33321934, 2020). "In addition, several DAMPs (e.g., HMGB1, S100A4, uric acid) can also enhance the expression of immunosuppressive mediators like interleukin (IL)-10 and indoleamine 2,3-dioxygenase (IDO) in stem cells, thereby inhibiting lymphocyte responses and contributing to tumor promotion." (PMID 31024543, 2019). "Overall, several mechanisms are described that explain discordance between intra- and extracellular HMGB1 levels, and it is currently not completely clear if measured serum HMGB1 levels are derived from a release through tumor cells or infiltrating immune cells from the tumor microenvironment." (PMID 30123419, 2018). "However, the present results did not exclude other effects of HMGB1 in tumor immune escape." (PMID 28968989, 2017). "These tumor-resident macrophages could sustain the inflammatory environment inside the tumor, together with neutrophils, contributing to enhance oxidative status trough the release of high amounts of ROS and activation of NOX2 in response to several DAMPs (for instance, HMGB1)." (PMID 27199982, 2016). "Thus, once tumor cells are exposed to HMGB1, chemotherapy fails to kill them." (PMID 26469759, 2015).
tumor (continued). "However, when we looked at potential DAMPs in 213Bi-treated MM cell supernatants, we could not detect any significant release of HMGB1, Hsp70, or TNFα or membrane expression of Hsp70, Hsp90, or calreticulin on irradiated tumor cells." (PMID 26539436, 2015). "However, few or no studies have focused on which redox status of HMGB1 could affect tumour angiogenesis." (PMID 26099505, 2015). "However, HMGB1 expression and function may not be the same in certain tumor cells and healthy cells." (PMID 24837834, 2014). "Although the expression of the other four ligands (HMGB1, CEACAM-1, LSECtin, and FGL-1) did not considerably affect the frequency of tumor-infiltrating CD8+ T cells, the negative relationship was consistent for the four important ligands." (PMID 38390332, 2024). "Due to the ROS generation via light irradiation to verteporfin in the LPNs, DAMP secretions such as HMGB1, ATP, and HSP70 were upregulated in CT26 tumor cells compared to the treatment without light." (PMID 39769944, 2024). "Despite the established roles of both HMGB1 and CXCL12 in tumor progression and metastatic spread to distal sites, the role of the CXCL12/HMGB1 heterocomplex in cancer has never been investigated." (PMID 38803493, 2024). "As a nonhistone protein, high mobility group box 1 (HMGB1) is widely present in the nucleus of mammalian cells, and has been found to play dual roles in tumor immunity, exerting pro- or antitumor immune effects." (PMID 39719600, 2024). "This study found that docetaxel enhanced CD8+ T-cell-mediated tumor cell killing but did not induce traditional markers of ICD such as ATP and HMGB1 but rather relied primarily on calreticulin translocation to the membrane." (PMID 39682260, 2024). "However, the binding of HMGB1 to DC TLR4 might be the signal driving the perception of the ICD by restricting the lysosomal degradation of the phagocyted material, then leading to the efficient processing and cross-presentation of dying tumor-derived antigens by DCs." (PMID 36429101, 2022). "Moreover, the replacement of cysteines 23, 45 and 106 by serine residues in HMGB1-ΔC-TM did not impact the anti-proliferative activity of HMGB1-ΔC, thus suggesting that the redox status of the recombinant proteins is not a key determinant for their direct activity on tumor cells." (PMID 35887213, 2022). "However, HMGB1 could promote the release of cytokines such as IL-6 and IL-8 by activating MAPK- and MyD88-dependent NF-KB pathways in the extracellular matrix, thus stimulating tumor cell proliferation, angiogenesis, epithelial-mesenchymal transition (EMT), invasion, and metastasis." (PMID 35273678, 2022). "For example, docetaxel treatment increased CTL-mediated killing of tumor cells via CRT translocation and increased antigen processing but did not induce DAMP (ATP or HMGB1) secretion required for ICD." (PMID 36497086, 2022). "HMGB1 expression was inversely correlated with HIPK2 and HMGB1 physically interacted with HIPK2 both in tumor or non-tumor tissues." (PMID 33747917, 2021). "Nano-DOX were first shown to stimulate the tumor cells and the TAMs to release the cytokine HMGB1 which, regardless of its source, acted through the RAGE/NF-κB pathway to induce PD-L1 in the tumor cells and PD-L1/PD-1 in the TAMs." (PMID 34488792, 2021). "The subsequent release of ATP and a non-histone chromatin protein, high-mobility group box 1 (HMGB-1), from the tumor cells provide adjuvant stimuli to the antigen presenting DC7." (PMID 29180759, 2017). "The results revealed that the expression levels of HMGB1, α-SMA, vimentin, and β-catenin were significantly increased in tumour tissue when compared with adjacent non-tumour tissue." (PMID 28727734, 2017). "Consistently, in nude mice bearing HMGB1-resistant HT29 xenograft tumours, treatment with non-cytotoxic L-DON doses and HMGB1 resulted in a sensitization of the xenografts to HMGB1." (PMID 26948869, 2016).
tumor (continued). "Stripping and re-probing the membrane with an anti-acetyl-lysine antibody showed that while no Ac-HMGB1 was detected in necrotic naïve HME cells, high level of Ac-HMGB1 was detected in the necrotic GemOE tumor cells." (PMID 26989079, 2016). "The univariate analysis revealed that tumor size, tumor differentiation, BCLC stage, peritumoral and intratumoral HMGB1 expression, and peritumoral TAM count, but not intratumoral TAM count, were independent prognostic factors for OS." (PMID 27836008, 2016). "However, the release of HMGB1 from dying cancer cells is not solely consistent with the establishment of anti-tumor immune responses as redox modifications induced by the cell or in the extracellular milieu, which may alter and even attenuate its DAMP activities." (PMID 26881822, 2016). "Thus, plasma HMGB1 might not exclusively derive from dying tumor cells." (PMID 27457217, 2016). "However, the expression levels of HMGB1 vary in different tumor types and evolve along with tumor progression, implying that some malignant cells may express HMGB1 to levels that are not compatible with the activation of TLR4 and RAGE in immune cells upon release." (PMID 25964783, 2015). "It has been found that tumor cells in muscle‐invasive bladder cancer patients who do not respond well to radiotherapy can secrete HMGB1 and interact with TLR4 of neutrophils to promote the production of NETs and the survival of tumor stem cells (CSCs), thus forming a feedback loop." (PMID 40979214, 2025). "Specifically, in the tumor cells of untreated tumors, we did not detect the HMGB1, whereas after ECT, we observed tumors regions with heightened HMGB1 levels as well as individual HMGB1 positive cells, indicative of immunogenic cell death." (PMID 40007542, 2025). "Thus, HMGB1 induces the appearance of active NK cells, as well as non-canonical CD4+ and CD8+-T lymphocytes, killing HLA-negative tumor cells that have escaped immune control." (PMID 38203798, 2024). "While our data suggest that oxidized tumor mitochondrial DNA is important in STING-mediated antitumor immunity after treatment by LID + US, we can not rule out that other DAMPs (e.g., HMGB1 and genomic DNA) may also play a role." (PMID 37391428, 2023). "Interestingly, whilst R28GFP GSCs spread from the core tumor throughout the brain, demonstrating the strong infiltrative ability of these cells, neither HMGB1, HSP70, YB-1 nor hexon stains were uniformly evident throughout the brain or the complete tumor." (PMID 37894279, 2023). "However, unlike the high level of HSP70 and HMGB1 in the sEV at 3 h after cryo-thermal therapy, the level of CD61 carried by sEV had no noticeable change in the tumor-bearing control group, at either 3 h or 24 h after cryo-thermal therapy." (PMID 34681680, 2021). "Interestingly, tumours developed in Ager−/− mice released smaller amounts of S100B, but not HMGB1, at 25 dpi compared with those derived from WT mice, suggesting that the presence of RAGE influences the secretion of S100B from tumour masses." (PMID 32159297, 2020). "Furthermore, conversely to HMGB1, HMGA1 is not released from apoptotic tumor cells, and its secretion clearly correlates with an invasive phenotype in TNBC cells." (PMID 31779212, 2019). "However, recombinant HMGB1-treated tumor cells were completely protected and survived DTX treatment, as compared to tumor cells without HMGB1." (PMID 26469759, 2015). "Most importantly, the same results were obtained when necrotic supernatants were added to live DU145 tumor cells undergoing DTX treatment, supporting our notion that dying cells release HMGB1 in the supernatant that can bind tumor cells to confer drug resistance through sCLU induction." (PMID 26469759, 2015). "HMGB1, being a nuclear nonhistone protein and an extracellularly secreted cytokine can interact with EPHB4, NF-κB, TLR4 and MIA, to promote cancer cell proliferation, migration, metastasis, innate immune response, and tumor escape while also affecting autophagy." (PMID 37511951, 2023).
tumor (continued). "Because our model does not include specific tumor antigens that can be presented by MHC to TCR, we cannot conclude that the increase of MHC expression is due to antigen overload, however, our simulation indicates an increase of MHC classes under HMGB1 simulation." (PMID 36993954, 2023). "However, our results revealed that S100A7/RAGE axis may play the same or stronger role in the tumor progression and metastasis of ESCC when the influence HMGB1 was absent." (PMID 34323409, 2021). "A recent study also reported that HMGB1 expression levels were higher in patients who did not respond to the immune checkpoint inhibitor ipilimumab than in responding patients, supporting a role of the HMGB1/RAGE axis in enabling a tumor-promoting microenvironment." (PMID 33256110, 2020). "To directly assess the role of Ac-HMGB1 secreted from GemOE tumor cells on induction of CXCR4 on the surface of MSCs, we again exposed early passage MSCs for 24 h to fresh HME medium supplemented or not with recombinant HMGB1 (rHMGB1, 10 μg/ml) that was in vitro acetylated." (PMID 26989079, 2016). "While in MIAPaCa-2 tumor cells no changes in VEGF gene expression were observed, significantly increased gene expression of PDGF was demonstrated after single or combined stimulation with the TLR ligands (ODN: FD = 2.5, p < 0.05; HMGB1: FD = 8.0, p < 0.005; ODN + HMGB1: FD = 2.4, p < 0.05)." (PMID 27941651, 2016). "However, HMGB1 could not protect anti-sense CLU-transfected DU145 tumor cells from DTX cytotoxicity, Thus, sCLU induction by HMGB1 mediates protection from DTX cytotoxity, resulting in drug resistance." (PMID 26469759, 2015). "However, the relevance between HMGB1 and VEGF-A in tumour angiogenesis has not been well studied." (PMID 26099505, 2015). "Moreover, HMGB1 levels were higher in patients who did not respond to the immune checkpoint inhibitor ipilimumab than in responding patients, supporting the hypothesis that the HMGB1/RAGE axis also leads to a tumor-promoting microenvironment." (PMID 36012593, 2022). "Hence, despite the lack of the “find-me” signal ATP, we propose that oxidized saline treatment could increase the in vivo immunogenicity of three tumor cell lines (but not non-malignant HaCaT keratinocytes) due to a significant increase in the ICD-markers CRT, HMGB1, and HSP70/9071." (PMID 30679720, 2019). "However, since our data shows that HMGB1 downregulation or the use of a soluble inhibitor did not lead to complete inhibition of tumour growth, it is very likely that signalling by other alarmins through TLRs or RAGE also have the ability to induce a tumour-promoting microenvironment." (PMID 27426915, 2016). "Furthermore, it has been shown that tumor-cell apoptosis induced by gemcitabine can enhance DC cross-presentation of tumor antigen to CD8+ T cells, but it is not yet clear whether CRT translocation, mobilization of HMGB1, and ATP are involved in the process." (PMID 22400040, 2012).